CCL27 (C-C motif chemokine ligand 27)
Diseases named in the same sentence as CCL27 in open-access papers (continued):
Sharing a sentence is not in itself a finding about the gene and the disease.
Cirrhosis (1 paper, 2022). A chronic disorder of the liver in which liver tissue becomes scarred and is partially replaced by regenerative nodules and fibrotic tissue resulting in loss of liver function. "ALD-cirrhosis was associated with IL-6, CCL27 and G-CSF and NAFLD-cirrhosis with LIF and CCL25." (PMID 36230823, 2022).
colitis (1 paper, 2012). Inflammation of the colon. "Interestingly, the expression of a set of genes encoding chemokines involved in homeostatic processes, including CCL21, CCL25, CCL27 and CCL28, was gradually down-regulated in our TNBS colitis model." (PMID 23226271, 2012).
cutaneous melanoma (1 paper, 2025). A primary melanoma arising from atypical melanocytes in the skin. "High expression of CCL27 in primary cutaneous melanomas is associated with enhanced T cell infiltration and has been linked to a 25% improvement in local tumor control rates following ICI therapy." (PMID 41346595, 2025). "In cutaneous melanoma, the skin-specific chemokine CCL27 plays a role in recruiting skin-homing T cells, including TRM cells, to the site of disease." (PMID 41346595, 2025).
endometrial tumors (1 paper, 2019). "All together, we showed that both cytokine and chemokine production in the endometrial tumors may participate to the alteration of NK cell function, as IL-6 and IL-1β are increased in the tumor, and recruitment, as chemoattractants CCL27, CXCL12, and CCL21 are significantly reduced in the tumor." (PMID 31105699, 2019).
eosinophilia (1 paper, 2009). "In our study CCL-17, CCL-27 and IL-18 serum levels correlated positively with total IgE in Group 2, and eosinophilia correlated positively with CCL-27." (PMID 19639049, 2009). "In AD patients below 10 years old (Group 1) a positive correlation between eosinophilia and CCL-20 (r = 0.53, P = .009) and IL-18 (r = 0.45, P = .03) was noted while in Group 2 eosinophilia correlated positively with CCL-27 (r = 0.52, P = .03)." (PMID 19639049, 2009).
exanthem (1 paper, 2021). A skin disease characterized by widespread, often symmetrical skin eruption that typically occurs acutely in association with a systemic disease, especially infectious or immune-mediated conditions. "This implicates CCL-27 in the pathogenesis of SJS/TEN, but elevated CCL27 levels were also identified in non-bullous drug-induced exanthems." (PMID 34577817, 2021).
hemorrhagic fever (1 paper, 2017). An infectious disease caused by certain viruses or bacteria that can damage the walls of tiny blood vessels, making them leak, and can hamper the blood's ability to clot and cause severe, life-threatening illness. "Hemorrhagic fever with renal syndrome cases were characterized by a strong expression of MIF, IL-12p40, IL-3, IL-16, CXCL9, CCL27, CXCL1, and HGF." (PMID 28572804, 2017).
hepatitis D (1 paper, 2025). "Other analyses of cytokine/chemokine profiles within cohorts with hepatitis D identified some cytokines and chemokines (e.g. CCL2 and CCL27) to be decreased in patients with high hepatitis D viraemia compared with patients with low viraemia." (PMID 39980752, 2025).
hepatocellular carcinoma (1 paper, 2020). A malignant tumor that arises from hepatocytes. "Chronic hypoxia does not affect CCL27/ESkine expression on the hepatocellular carcinoma cells model." (PMID 32781743, 2020).
influenza (1 paper, 2025). An acute viral infection of the respiratory tract, occurring in isolated cases, in epidemics, or in pandemics; it is caused by serologically different strains of viruses (influenzaviruses) designated A, B, and C, has a 3-day incubation period, and usually lasts for 3 to 10 days. "Both CCL27 and CCL28 have also been shown to provide immunity against influenza and HIV due to the fact that adjuvant activity is dependent on CCR10-expressing plasma B cells that produce IgA and accumulate at mucosal surfaces." (PMID 40975172, 2025).
kidney failure (1 paper, 2018). An acute or chronic condition that is characterized by the inability of the kidneys to adequately filter the blood. "Future work should test the likelihood that CCL27 can serve as a biological marker for patients who are at excessive risk for progressive decline in kidney function and whether blocking CCL27 may retard progression to kidney failure." (PMID 30214382, 2018).
lichen sclerosus (1 paper, 2025). "Blocking the CCR10/CCL27 interaction could represent a potential strategy to prevent inflammatory processes in lichen sclerosus." (PMID 41301909, 2025). "CCL27, along with MARCO, was among the most upregulated genes identified in lichen sclerosus." (PMID 41301909, 2025).
mild cognitive impairment (1 paper, 2023). "Chemokines CCL1, CCL2, CCL15, CCL27, CXCL9, CXCL10, and CX3CL1 might be most promising to serve as key molecular markers of cognitive impairment, although more cohort studies with larger populations are needed." (PMID 37291639, 2023).
Parkinson disease (1 paper, 2022). A progressive degenerative disorder of the central nervous system characterized by loss of dopamine producing neurons in the substantia nigra and the presence of Lewy bodies in the substantia nigra and locus coeruleus. "Previous MR studies on Alzheimer’s disease suggest potential causal associations with BIN1, CCL27, C3, CD33, CD4 T cells, GDF-15 and SVEP1, whereas MR studies on Parkinson’s disease suggest a potential causal association with GPNMB, IL-6 and MIP1b." (PMID 37118290, 2022).
pemphigus (1 paper, 2022). Pemphigus is a group of rare autoimmune diseases that cause blistering of the skin and mucous membranes (mouth, nose, throat, eyes, and genitals).This conditioncan occur at any age, but often strikes people in middle or older age. "Notably, CCL19, CCL26, CCL27 and CXCR5 were highly expressed chemokines and chemokine receptors detected in pemphigus group." (PMID 35449056, 2022).
periodontitis (1 paper, 2021). An acute or chronic inflammatory process that affects the tissues that surround and support the teeth. "As mentioned, not only IL-6 levels but also CCL27 and CXCL13 high levels were previously associated with periodontitis." (PMID 35048045, 2021).
psoriatic arthritis (1 paper, 2017). Joint inflammation associated with psoriasis. "Patients with nail involvement had higher CXCL10 expression; longer duration of the disease was associated with further decrease of CCL27 in areas that were not affected with psoriatic rash; and psoriatic arthritis was associated with lower IFIH1 expression." (PMID 28790368, 2017).
radiation-induced dermatitis (1 paper, 2025). "In radiation-induced dermatitis, CCR10 supports ILC maintenance and limits inflammation, and ionizing radiation upregulates keratinocyte CCL27 via a TNF-α–ROS feedback loop." (PMID 41050670, 2025).
rosacea (1 paper, 2022). A chronic erythematous skin disorder that affects the face. "TNF-α and IL-1β are known to induce the expression of a subset of proinflammatory chemokines (CXCL1, CXCL8, CCL20, and CCL27) in keratinocytes, implying a potential pathway for TH1 and TH17 cell recruitment as well as neutrophil recruitment in rosacea lesional skin." (PMID 35832851, 2022).
skin changes (1 paper, 2020). "In line, no alterations in measured serum chemokine levels (IL-17A/F, IL-23, IL-18, CCL20, and CCL27) were observed either, confirming a weak relationship between serum cytokines and skin changes in all but most severely affected individuals." (PMID 33343564, 2020).
tuberculosis (1 paper, 2014). A chronic, recurrent infection caused by the bacterium Mycobacterium tuberculosis. "CTAK/CCL27 is a cytokine associated with T cell activation and migration and is elevated in severe tuberculosis cases." (PMID 25277705, 2014).
ulcers (1 paper, 2023). "As such, increased CCL27 may perhaps play a role in MA-associated skin damage, including itching (due to meth mites), lesions, excoriations, and ulcers." (PMID 37996407, 2023).
viral infection (1 paper, 2024). "Chemokine C–C motif chemokine ligand 27 (CCL27) is downregulated in the acute stage of viral infection." (PMID 37831367, 2024). "With the cutoff threshold of ≤ 0.05 p value and 1.41-fold change, ICAM1 and CCL27 were the most significantly increased and decreased proteins, respectively, in the viral infection category." (PMID 37831367, 2024). "It was interesting to note that CCL27 and BMP7 are down in the acute phase of viral infection as this may result in amplified virus infection." (PMID 37831367, 2024).
tumor (42 papers, 2012 to 2026). "In colorectal cancer, epithelial STAT3 loss increases CCL28, enhancing Treg migration, while CCL27-driven Th22 recruitment and IL-22 production, support tumor progression." (PMID 41050670, 2025). "In skin tumors, loss of CCL27, a chemokine constitutively expressed by normal keratinocytes, impaired T-cell homing to cutaneous tumors accelerating tumor outgrowth in a tumor mouse model of B16F10 melanoma." (PMID 33262763, 2020). "CCL28 and CCL27 participate in the anticancer response of the immune system, causing an infiltration of the tumor by anticancer NK cells, which leads to improved prognosis with an increased expression of these chemokines in the tumor." (PMID 33076281, 2020). "Further research is needed to elucidate the molecular and biological functions of CCL27 in tumor metastasis." (PMID 40296873, 2025). "Serum levels of CTACK/CCL27 were found to be higher in patients with plaque or tumor-stage lesions than in those with patch-stage MF." (PMID 40861461, 2025). "Lymphatic endothelial cells (LECs) expressing CCR10, regulated by VEGF-D and TNF-α migrate towards tumor-derived CCL27 and CCL28; VEGF-D is essential for in vivo lymphatic vessel formation and metastasis." (PMID 41050670, 2025). "For example, CCR10 expression does not appear to change significantly with disease stage, although CCL27 levels are lower in patch lesions compared to plaque and tumor-stage lesions." (PMID 40861461, 2025). "CXCL13, IL36γ, and CCL27 expression in the G4 tumor was higher than in the normal brain and other MB subgroups." (PMID 35563678, 2022). "The results above delineate the alteration of SPTBN2 and BCL2L1 in view of tumor immune modulation mediated by CCL27 and CCR10, resulting in a reduced abundance of CD4+ T cells and dendritic cells." (PMID 34179092, 2021). "We also investigated the presence of CXCL12, CCL21, CXCL11, IP-10 (or CXCL10), CCL19, and CCL27, which participate to the recruitment of specific NK cell populations to the tumor site." (PMID 31105699, 2019). "Incubating tumor cells with a neutralizing antibody for CCL27, one of the ligands of CCR10, prevented tumor formation." (PMID 30420855, 2018). "For example, classical chemokines and their cognate receptors CXCL12-CXCR4, CCL19/CCL21-CCR7 and CCL27/CCL28-CCR10 have been reported to promote the metastasis of tumor cells to normal lungs, lymph nodes and skins, respectively." (PMID 27329720, 2016). "Further, in vivo work demonstrated that neutralization of CCL27 decreased leukocyte recruitment toward cutaneous tumor sites, resulting in enhanced tumor growth." (PMID 27807435, 2016). "Because immunotherapy using NK cells suffers from the inability of these cells to migrate into tumor stroma, it is now feasible to direct these cells toward sites of tumor growth, particularly those secreting CCL27 and CCL28." (PMID 27807435, 2016). "Having established that CCR10 activation promote proliferation and invasion in vitro, we evaluated the contribution of CCL27/CCR10 signaling on tumor growth in vivo by using experimental intracranial models." (PMID 25149529, 2014). "While there is substantial evidence supporting the involvement of S100A9 in the tumor immune microenvironment and immune evasion, the roles of CCL27, ID4 and LRP4, genes that also showed strong correlations with infiltrating immune cells, remain inadequately explored." (PMID 40296873, 2025). "CCL27 could inhibit tumor growth to a certain extent through recruiting natural killer cells or T cells locally and could intensify the resistance to tumor formation as well." (PMID 34179092, 2021). "Since CCL20 showed the most prominent Ras-dependent upregulation among all tested chemokines, and previous findings supported a role for CXCL14 and CCL27 in tumour-immune surveillance, we decided to investigate further the role of CCL20 within the tumour microenvironment." (PMID 32601464, 2020).
tumor (continued). "Previously, we demonstrated that activation of EGFR/Ras led to the downregulation of the homoeostatic chemokine CCL27 in transformed keratinocytes, resulting in significantly impaired recruitment of tumour-targeting leukocytes, leading to evasion from tumour-immune surveillance." (PMID 32601464, 2020). "The combination treatment caused increased secretion of CCL2, CCL21, CXCL1, CXCL2, CXCL5, CXCL9 and CXCL16, whereas the levels of CCL11, CCL17, CCL19, CCL22, CCL25, CCL27 and CX3CL1, which are associated with protumourigenic effects, were decreased in the tumours." (PMID 33014356, 2020). "We showed that both chemokines (CXCL12, IP-10, and CCL27) and cytokines profiles (IL-1β and IL-6) were altered in the tumor microenvironment and might reduce NK cell function and recruitment to the tumor site." (PMID 31105699, 2019). "Indeed, CCL27 and other NK chemoattractant molecules are less produced by the tumor microenvironment than by the adjacent tissue." (PMID 31105699, 2019). "We hypothesize that the significant rise in CCL27 expression found in these patients facilitates oligomerization at the receptor level leading to specific, pro-tumor signaling." (PMID 27732933, 2016). "Consequently, NK cells can be targeted toward the growth of tumor cells that secrete CCL27 and CCL28." (PMID 27807435, 2016). "However, numerous in vitro studies show that CCL28 and CCL27 support tumor development." (PMID 33076281, 2020). "CCL27 is involved in the general immune response and is a dominant player in tumor immunity; thus, its level might not be associated with a change in EBV VCA-IgA." (PMID 29295705, 2018). "This review compiles current knowledge on the significance of lesser-known chemokines in MM tumor processes, including CXCL13, CCR2 ligands (CCL2 [MCP-1], CCL7 [MCP-3]), CCL4, CCL5 (RANTES), CCL17, CCL20, CCL27, CCL28, and CX3CL1 (fractalkine)." (PMID 41749925, 2026). "Quantitative evaluation revealed consistent downregulation of ADH1B, CCL27, ID4 and LRP4 in tumor tissues compared to normal counterparts." (PMID 40296873, 2025). "In solid tumors, the stromal components and chemokines (e.g., CCL27, CXCL12) often prevent the infiltration of NK cells into the tumor core, limiting their ability to exert cytotoxic effects." (PMID 40076725, 2025). "In summary, our findings reveal that four of the identified characteristic genes (ADH1B, CCL27, ID4 and LRP4) are consistently downregulated in cSCC, and prior studies suggest their involvement in tumor proliferation, migration and invasion." (PMID 40296873, 2025). "CCL27 protein was detected in 16 of 20 (80%) nasopharyngeal tissue samples from VCA-IgA–positive healthy donors and in 3 of 20 (15%) tumor tissue samples from NPC patients." (PMID 29295705, 2018). "CCR10, the receptor for the chemokines CCL27/CTACK and CCL28/MEC, belongs to the chemokine receptor subfamily of GPCRs and is thought to function in immune responses and tumour progression." (PMID 26941067, 2016). "The chemokine receptors, CCR10 and CCR4, known to respond to chemo-attractants CCL27, MCP-1, and CCL22, have been shown to be critical in inducing mobilization and homing of myeloid cells and leukocytes to the tumor site." (PMID 23372791, 2013). "For example, tumor VEGF-D synthesis upregulates C-C motif chemokine receptor type 10 (CCR10) expression and increases LEC migration towards tumor-derived chemokine ligands 27 and 28 (CCL27/28)." (PMID 38201272, 2023). "The lower levels of NK cell chemoattractants (CCL27, CCL21) in the tumor microenvironment may participate to the immunosuppressive mechanism of the tumor by limiting cytolytic cell recruitment." (PMID 31105699, 2019). "High expression of CCL27 protein was observed in 16 of 20 (80%) in nasopharyngeal epithelium from VCA-IgA–positive healthy donors, and no expression of CCL27 protein was observed in 17 of 20 (85%) tumor tissues from NPC patients." (PMID 29295705, 2018).
tumor (continued). "Similarly, CXCL5, CXCL13, CCL1, CCL7 and CCL26 in WF collected from patients with T1–2 tumor tend to be higher than those with Tis, and the profiles of CXCL13, CCL27, MMP-1 and MMP-7 in WF from N1–3 patients tend to be higher than those with N0." (PMID 26313265, 2015). "We also found that CXCL12, CCL27, and CCL21 were found in higher quantities in the healthy adjacent tissue (1795.6 ± 700 pg/ml, 242.9 ± 95 pg/ml, and 17285.9 ± 6000 pg/ml, respectively) than in the tumor (325.8 ± 72 pg/ml, 56.7 ± 20 pg/ml, and 2313.6 ± 1,000 pg/ml, respectively)." (PMID 31105699, 2019). "Of note, CCL27 levels did not correlate with tumor load (data not shown)." (PMID 27732933, 2016).
cancer (24 papers, 2015 to 2026). A tumor composed of atypical neoplastic, often pleomorphic cells that invade other tissues. "The results show that in most cancers, the expression of chemokine CCL27 and POLD2 are positively correlated (p < 0.05)." (PMID 36081989, 2022). "Additionally, EHMT2 loss increased the expression of chemokines such as CXCL10 and CCL27 in cancer cells, promoting NK cell migration." (PMID 41366520, 2026). "Furthermore, the expression of NKG2D ligand MICB (Fig. EV8F,G) and chemokines CXCL10 and CCL27 (Fig. EV8H) was increased following treatment of cancer cells with BRD4770." (PMID 41366520, 2026). "Furthermore, comprehensive pan-cancer analysis indicated that GPR141 expression exhibited substantial associations with numerous chemokine family members, excluding CCL1, CCL16, and CCL27." (PMID 40959105, 2025). "CCL28 and CCL27 stimulate proliferation and have anti-apoptotic effects on cancer cells." (PMID 33076281, 2020). "However, the molecular and biochemical signaling pathways by which CSC-DC vaccination induces down-regulation of CCR10 on cancer cells, particularly on cancer stem cells, and down-regulation of CCL27 and CCL28 in metastatic target organs have yet to be identified." (PMID 29423335, 2017). "TUBA1C was coexpressed with most chemokines except CCL27, and coexpression of TUBA1C with chemokines and chemokine receptors was observed in most cancers except UVM (C, D)." (PMID 35513790, 2022). "For other chemokines, CXCL11 was positively related to approximately all other chemokines except CCL14, CCL15, CCL16, CCL27, CCL28, CXCL6, and CXCL17 in almost all types of cancers." (PMID 35935945, 2022). "Due to the production of CCL28 and CCL27 in the skin, the expression of CCR10 on a cancer cell increases the probability of skin metastasis." (PMID 33076281, 2020). "Moreover, we found that USP5 showed certain correlation with majority of chemokines with the exception of CCL1, CCL16, CCL27, CCL24 and CCL25 in pan-cancer." (PMID 37268697, 2023). "CCL15, CCL14, CCL16, CCL23, and CCL27 showed negative relations in more than 10 cancers." (PMID 38655053, 2024). "For this reason, it may increase the sensitivity of cancer cells to CCL28/MEC and CCL27/ESkine." (PMID 32781743, 2020). "CCL27 and CCL15 showed negative correlations with necroptosis levels in certain cancers." (PMID 36170029, 2022).